CXCL1P1 (C-X-C motif chemokine ligand 1 pseudogene 1)
Synonyms: MGSAP; GROP; GRO1P; formerly SCYB1P; CXCL1P
Gene: Processed pseudogene on chromosome 4 (73,944,011 to 73,944,324, reverse strand). Ensembl gene ENSG00000250339.
Diseases named in the same sentence as CXCL1P1 in open-access papers:
CXCL1P1 is named in the same sentence as 5 diseases in open-access papers, as found by Europe PMC text mining. Sharing a sentence is not in itself a finding about the gene and the disease.
CXCL1P1 shares sentences with these, for which no sentence is quoted: cancer (2 papers); infection (2); colorectal cancer (1); dental caries (1); tumor (1).